DPP4 (dipeptidyl peptidase 4)
Diseases named in the same sentence as DPP4 in open-access papers (continued):
Sharing a sentence is not in itself a finding about the gene and the disease.
adenoma (5 papers, 2010 to 2022). A neoplasm arising from the epithelium. "According to the colonoscopy findings, sCD26 and DPP4 activity progressively decreased in advanced adenomas and CRC, with statistically significant differences, even between both groups; 918 of them had a FIT result (n = 596 positive cases) with approximately 70% of these (n = 412) false positives." (PMID 36230486, 2022). "In both cases, the adenoma group showed the highest levels of DPP4 activity and anti-CD26 isotypes." (PMID 32051696, 2020). "Interestingly, patients with advanced adenomas displayed the most elevated mean levels of anti-CD26 IgA, IgM, and particularly IgG (Mann-Whitney U test, p = 0.030) in comparison with the other FIT positives without adenomas, and these levels did not correlate with sCD26 or its DPP4 activity." (PMID 32051696, 2020).
aneurysm (5 papers, 2015 to 2021). Bulging or ballooning in an area of an artery secondary to arterial wall weakening. "Further, some neuronal and several specific immune-related processes were inversely and directly associated with DPP4, respectively, specifically in the aneurysm." (PMID 31971988, 2020). "An anti-inflammatory DPP-4 (dipeptidyl peptidase-4) inhibitor (anagliptin) has been shown to reduce aneurysm growth through NF-κ-B and ERK5 signaling involving IL-6." (PMID 33923626, 2021). "It was observed that DPP4 expression correlated with typical aneurysm disease processes, such as a high degree of inflammation, ECM degradation and organization and peptidase activity." (PMID 31971988, 2020). "In another study, DPP4 inhibition decreased the formation of aneurysm, elastin degradation, expression of MMP2 and -9, gelatinolytic activity, aortic apoptotic signal and macrophage infiltration in a mouse model, with similar results shown for GLP-1." (PMID 31971988, 2020). "We showed an increased medial and adventitial gene expression of DPP4 in AAA compared with controls, and demonstrated DPP4 activity in the human aneurysm vessel wall." (PMID 31971988, 2020). "Animal studies have suggested that inhibitors of DPP4 are protective against aneurysm development and suppresses many typical aneurysm disease processes." (PMID 31971988, 2020). "Animal studies have shown that treatment with DPP4 inhibitors can suppress the development and the progression of experimental aneurysms." (PMID 31971988, 2020). "In patients enrolled in our study, only 163 individuals were prescribed with DPP-4 inhibitors in the aneurysm group, and 187 in the control group." (PMID 27585542, 2016). "The most important finding of our study, we strengthen the protective role of DPP-4 inhibitor, sitagliptin, in anti-aneurysm action by propelling the advancement of active GLP-1 with working on macrophages." (PMID 25876091, 2015). "The reason why an increased expression of DPP4 in the aneurysm wall was observed might be a reflection of the infiltrating inflammatory cells, which is one of the hallmarks of the disease." (PMID 31971988, 2020). "While an increased activity does not equal increased expression, a speculative explanation could be recruitment of inflammatory cells into the aneurysm wall, thus decreasing their presence in plasma and resulting in a lower DPP4 activity when measured." (PMID 31971988, 2020). "This could at least in part be explained by a decreasing amount of SMCs in AAA with increasing inflammation, thus would the total relative SMC-related mRNA concentration decrease, even as SMCs do appear to express DPP4 in the aneurysm." (PMID 31971988, 2020). "Despite the absence of a positive association in the microarray data, DPP4 co-localized with B-cells and SMCs in the aneurysm wall." (PMID 31971988, 2020). "In the same study, anagliptin, a dipeptidyl peptidase-4 (DPP-4) inhibitor and a known anti-atherogenic agent, inhibited the accumulation of macrophages in the walls of aneurysms and also diminished the size of aneurysms in mice." (PMID 34200256, 2021). "DPP4 is upregulated in both media and adventitia of human AAA and correlates with aneurysm pathophysiological processes." (PMID 31971988, 2020). "In the control adventitia, DPP4 was inversely related to processes involving vasoconstriction/-dilatation, which was not seen in the aneurysm adventitia." (PMID 31971988, 2020). "DPP4 gene expression further correlated with the expression of genes related to typical AAA processes and the protein was expressed by macrophages, T-cells, B-cells and SMCs in aneurysm tissue." (PMID 31971988, 2020). "However, there are no reports showing the expression and activity of DPP4 in human aneurysm tissue." (PMID 31971988, 2020).
Cholecystitis (5 papers, 2016 to 2025). The presence of inflammatory changes in the gallbladder. "Two meta-analyses in 2022 also confirmed that DPP-4 inhibitors significantly increase the risk of gallbladder/biliary diseases and cholecystitis." (PMID 40041492, 2025). "A previous European Medicines Agency Assessment Report also suggested a strong association between DPP4 inhibitor use and the risk of cholecystitis." (PMID 36271423, 2022). "Current studies suggest that DPP4 inhibitor use increases the risk of cholecystitis, which is consistent with our present results." (PMID 36271423, 2022). "The results shown here may be due to the course of chronic cholecystitis with multiple exacerbations and recurrent episodes of acute inflammation associated to minimal pain, which can alter the secretion of DPP-4." (PMID 31100960, 2019). "Due to stimulation of cholangiocytes′ proliferation by GLP-1, GLP-1 analogues and DPP-4 inhibitors used in the management of T2DM increase the risk of gallbladder and bile duct diseases such as cholangitis, cholecystitis, choledocholithiasis, and gallbladder cancer." (PMID 36360537, 2022). "A meta-analysis and systematic review encompassing 82 randomized controlled trials revealed a significant association between DPP-4 inhibitors and an increased risk of cholecystitis, while no such association was found with an increased risk of cholecystolithiasis or other biliary diseases." (PMID 40041492, 2025).
colon adenocarcinoma (5 papers, 2011 to 2021). "DPP4 expression was significantly lower in breast invasive carcinoma, kidney chromophobe, cholangiocarcinoma, colon adenocarcinoma, and LUSC." (PMID 33614513, 2021).
diabetic neuropathy (5 papers, 2013 to 2024). A chronic, pathological complication associated with diabetes mellitus, where nerve damages are incurred due to diabetic microvascular injury involving small blood vessels that supply these nerves, resulting in peripheral and/or autonomic nerve dysfunction. "In humans, DPP-4 inhibitor was found to be superior to sulfonylurea drugs in preventing diabetic neuropathy." (PMID 36082275, 2022). "Currently, there are no available large randomized clinical trials focusing on the effects of DPP-4 inhibitors on diabetic neuropathy." (PMID 32190049, 2020). "We suppose that both reductions of FPG and vasodilatation, a direct action of DPP-4 inhibitors, leads to improved nerve blood flow and nerve fiber damage in patients with diabetic neuropathy." (PMID 23432786, 2013). "Animal studies showed promising beneficial effects of DPP-4 inhibitors on diabetic neuropathy." (PMID 32190049, 2020).
glucose metabolism disorder (5 papers, 2019 to 2025). "We subsequently discovered that miR-548ag is upregulated in obese individuals and contributes to glucose metabolism disorders by targeting DNMT3B, thereby upregulating DPP4 expression in the liver." (PMID 40339699, 2025).
hyperthyroidism (5 papers, 2016 to 2023). Overactivity of the thyroid gland resulting in overproduction of thyroid hormone and increased metabolic rate. "The current study revealed that DPP-4 inhibitors are also associated with a decreased risk of amiodarone-induced hyperthyroidism in the analysis of the subset data and logistic regression analysis." (PMID 32132864, 2020). "The present study aimed to investigate the relationship between serum concentration and activity of DPP4 and the severity of hyperthyroidism in GD patients." (PMID 37350750, 2023). "This study aimed to investigate the relationship between serum concentration/activity of DPP4 and the severity of hyperthyroidism in GD patients." (PMID 37350750, 2023). "And increased serum concentration and activity of DPP4 was positively related with the severity of hyperthyroidism in GD patients." (PMID 37350750, 2023). "Hyperthyroidism resulted in a decrease of DPP4 activity, while an increase was observed in hypothyroidism in both wild type SHR and SHRM, regardless of the sex." (PMID 35885012, 2022). "Further studies are needed to clarify the association between DPP-4 inhibitors and hyperthyroidism and elucidate the mechanism of the effect of DPP-4 inhibitors on hyperthyroidism." (PMID 32132864, 2020). "Therefore, the results suggested that the serum concentration and activity of DPP4 was increased and positively related with the severity of hyperthyroidism in GD patients." (PMID 37350750, 2023). "DPP-4 inhibitors (adjusted ROR 0.32, 95% CI 0.10-1.00) and metformin (adjusted ROR 0.46, 95% CI 0.34-0.62) were inversely associated with amiodarone-associated hyperthyroidism and interstitial lung disease, respectively." (PMID 32132864, 2020). "Metformin (ROR 0.62, 95%CI 0.43-0.89; IC -0.63, 95%CI -1.14 to -0.11), sulfonylureas (ROR 0.53, 95%CI 0.32-0.85; IC -0.85, 95%CI -1.53 to -0.17), and DPP-4 inhibitors (ROR 0.25, 95%CI 0.08-0.78; IC -1.66, 95%CI -3.08 to -0.23) were inversely associated with amiodarone-associated hyperthyroidism." (PMID 32132864, 2020). "In the logistic regression analyses, DPP-4 inhibitors (adjusted ROR 0.32, 95% CI 0.10-1.00) and metformin (adjusted ROR 0.46, 95% CI 0.34-0.62) were inversely associated with amiodarone-associated hyperthyroidism and interstitial lung disease, respectively." (PMID 32132864, 2020). "However, the logistic regression analyses identified a significant inverse association between DPP-4 inhibitors and hyperthyroidism but not between the other antidiabetic drugs and hyperthyroidism." (PMID 32132864, 2020). "A search of the PubMed database using the terms “DPP4 inhibitors”, “thyroid”, “TSH”, “hypothyroidism”, and “hyperthyroidism” did not yield any studies related to TSH changes with DPP4 inhibitors." (PMID 27403442, 2016).
influenza (5 papers, 2018 to 2023). An acute viral infection of the respiratory tract, occurring in isolated cases, in epidemics, or in pandemics; it is caused by serologically different strains of viruses (influenzaviruses) designated A, B, and C, has a 3-day incubation period, and usually lasts for 3 to 10 days. "Meanwhile, the increase in DPP4 (MERS-CoV), ST3GAL4, and ST6GAL1 (influenza) was associated with increased goblet and basal activated cells." (PMID 34198852, 2021).
lactic acidosis (5 papers, 2013 to 2025). Metabolic acidosis characterized by the accumulation of lactate in the body. "Additional options include metformin (with caution in patients at risk of lactic acidosis) and DPP-4 inhibitors." (PMID 40218153, 2025). "In addition, lactic acidosis occurred in the patients prescribed DPP-4 inhibitors after PI revision but not in patients prescribed metformin with moderately decreased kidney function (30 ≤ eGFR <60 mL/min/1.73m2) before and after PI revision." (PMID 38327270, 2023).
metastatic prostate carcinoma (5 papers, 2016 to 2021). A carcinoma that arises from the prostate gland and has spread to other anatomic sites. "This suggests that inhibition of DPP4 with this targeted class of anti-diabetic drugs may provide a resistance mechanism in patients with metastatic prostate cancer." (PMID 34055551, 2021). "Circulating DPP4 activity was recently targeted to treat patients with metastatic prostate cancer." (PMID 27654253, 2016). "For example, a low-molecular-weight inhibitor of DPP4 activity was found in sera from patients with metastatic prostate cancer, perhaps related to glypican-3, recently reported as a natural inhibitor of CD26/DPP4 enzymatic activity, usually absent in adult tissues though expressed in many tumours." (PMID 32051696, 2020).
oral cancer (5 papers, 2015 to 2024). "The present study aims to assess the levels of DPP-4 in serum and saliva of individuals with both lesions to explore its potential as a diagnostic biomarker for early oral cancer detection, distinguishing it from OPMLs and healthy subjects." (PMID 39390508, 2024). "Taken together, we suggest that the DPP4 rs7608798 or rs2268889 SNP might result in decreased DPP4 expression and subsequently cause progression of PCa and oral cancer." (PMID 37533175, 2023). "Therefore, a potential mechanism linking a reduced risk of oral cancer after sitagliptin use is through its inhibition of the activity of DPP-4 in oral mucosa." (PMID 29228568, 2017). "The remarkable diagnostic accuracy of both serum and salivary DPP-4 in discriminating between OSCC, OPMLs, and healthy controls suggests its potential utility as a well-established marker for early oral cancer diagnosis." (PMID 39390508, 2024). "The remarkable diagnostic accuracy of both serum and salivary DPP-4 in discriminating OSCC from OPMLs and healthy control could suggest its potential utility as a well-established marker for early oral cancer diagnosis." (PMID 39390508, 2024). "It is worthwhile to investigate such enzyme activity in these patients and to see whether DPP-4 inhibitors may prevent the development of or have a therapeutic role on oral cancer." (PMID 29228568, 2017). "In addition, serum DPP4 levels is increased in patients with hepatic cancer and decreased in patients with blood, solid and oral cancer." (PMID 26471376, 2015). "In addition to PCa, the tumour‐suppressive role of DPP4 was also demonstrated in oral cancer, as evidenced by the fact of a reduction in migration of DPP4‐overexpressing SCC9 oral cancer cells." (PMID 37533175, 2023).
osteoarthritis (5 papers, 2006 to 2025). A noninflammatory degenerative joint disease occurring chiefly in older persons, characterized by degeneration of the articular cartilage, hypertrophy of bone at the margins and changes in the synovial membrane. "In osteoarthritis, Dipeptidyl peptidase 4 (DPP4) competitively binds to MYH9, preventing its ubiquitination." (PMID 39680708, 2025). "The plasma level of DPP4 was lower than that in osteoarthritis and negatively correlated with plasma inflammation marker C-reactive protein." (PMID 35309368, 2022). "A serial of studies reported that DPP4 is associated with chondrocyte physiology and inhibition of DPP4 suppresses the degradation of ECM, which is considered to help the amelioration of osteoarthritis." (PMID 35309368, 2022). "Sitagliptin treatment could selectively target and eliminate DPP‐4+ senescent chondrocytes, consequently leading to suppression of osteoarthritis progression." (PMID 38556837, 2024). "The decrease of DPP4 activity also occurs in synovial fluids, fluid mononuclear cells (FMNC) and synovial membrane in RA compared with osteoarthritis." (PMID 35309368, 2022).
schizophrenia (5 papers, 2013 to 2025). A major psychotic disorder characterized by abnormalities in the perception or expression of reality. "A genome-wide association study found that six immune candidates, namely, DPP4, HSPD1, EGR1, CLU, ESAM, and NFATC3, were associated with schizophrenia." (PMID 35757702, 2022).
tuberculosis (5 papers, 2015 to 2023). A chronic, recurrent infection caused by the bacterium Mycobacterium tuberculosis. "Even though the effect on blood glucose levels through the use of DPP4 blockers during TB-T2D on the host response to M. tuberculosis infection has not been addressed, the hormonal control of appetite and blood glucose may cause modulation of the of immune response." (PMID 31637222, 2019). "The data suggest that in TB, CXCL10 is secreted by M. tuberculosis-infected macrophages, and undergoes rapid inactivation by membrane bound DPP4 (CD26) expressed on co-localized CD4+ T cells." (PMID 30026741, 2018).
Ureteral obstruction (5 papers, 2016 to 2025). Obstruction of the flow of urine through the ureter. "Consistently, DPP4 was significantly increased in the unilateral ureteral obstruction (UUO) injured kidney in vivo and human epithelial kidney HK-2 cells under Ang II stimulation in vitro." (PMID 40607249, 2025). "In the present study, we examined the therapeutic effects of DPP-4 inhibition in mice with unilateral ureteral obstruction (UUO), a nondiabetic model of progressive renal fibrosis." (PMID 28118775, 2017).
aortic stenosis (4 papers, 2021 to 2025). Aortic valve stenosis is a aortic valve disease caused by the incomplete opening of the aortic valve. "Lower levels of DPP4 were also associated with worse left ventricular function, higher New York Heart Association functional class, and low-flow, low-gradient aortic stenosis." (PMID 41141478, 2025). "Additionally, several drugs are under investigation as potential options for slowing the progression of aortic stenosis, including evolocumab and dipeptidyl peptidase-4 inhibitors." (PMID 39456826, 2024). "Indeed, we found in our present experiments that the HFD + VitD group showed an increase in the plasma DPP-4 activity by approximately 2-fold when compared with the control group at 6 and 12 weeks, further supporting the involvement of DPP-4 activity in the pathogenesis of aortic stenosis." (PMID 33401457, 2021).
aortic valve calcification (4 papers, 2021 to 2025). "Interestingly, a dipeptidyl peptidase-4 (DPP-4) inhibitor could ameliorate aortic valve calcification by preventing IGF1 degradation, rendering it potentially a new agent for valve calcification disease." (PMID 36237897, 2022).
arteriosclerosis (4 papers, 2016 to 2021). A vascular disorder characterized by thickening and hardening of the walls of the arteries. "The effects on arteriosclerosis of other anti-diabetic agents, such as pioglitazone and dipeptidyl peptidase 4 (DPP-4) inhibitors, have been evaluated in randomized clinical trials using surrogate markers, such as carotid intima-media thickness (IMT)." (PMID 27619983, 2016). "Although the anti-inflammatory effects of DPP-4 inhibitors in vivo and in vitro have been reported, few in vitro studies have examined the effects of linagliptin using monocytes, which play a central role in arteriosclerosis-related inflammation." (PMID 30151063, 2018). "Compared with previous studies that examined the effects of DPP-4 inhibitors administered once per day on vascular endothelial functions, patients in this study had a longer duration of DM, and thus, potentially more advanced arteriosclerosis." (PMID 27809903, 2016).
autism (4 papers, 2011 to 2022). Persistent deficits in social interaction and communication and interaction as well as a markedly restricted repertoire of activity and interest as well as repetitive patterns of behavior. "Although DPP4 had never been directly associated with autism, some findings link it to autistic features." (PMID 28358038, 2017).
cardiomyopathy (4 papers, 2016 to 2024). A disease of the heart muscle or myocardium proper. "Sitagliptin, a dipeptidyl peptidase-4 (DPP-4) inhibitor, has also been suggested as an effective anti-diabetic medication for cardiomyopathy." (PMID 38255895, 2024).
celiac disease (4 papers, 2012 to 2022). An autoimmune genetic disorder with an unknown pattern of inheritance that primarily affects the digestive tract. "A DPP4 breath test could establish a role for DPP4 in coeliac disease, and could be used as an early detection tool in paediatric patients." (PMID 30894647, 2019). "Furthermore, DPP4 can be used as a preparation to cleave difficult-to-hydrolyze proline-rich peptides under conditions corresponding to those of the human gut, and may, therefore, be considered as a potential candidate for the enzyme therapy of celiac disease." (PMID 34575782, 2021).